ZNF525 (zinc finger protein 525)
Description:
May be involved in transcriptional regulation.
Synonyms: KIAA1979
Tractability: PROTAC: ubiquitination databases record sites on it.
Gene: Protein-coding gene on chromosome 19 (53,365,693 to 53,392,217, forward strand). Ensembl gene ENSG00000203326.
Subcellular location: Nucleus
Gene Ontology:
Molecular function: DNA-binding transcription factor activity; RNA polymerase II cis-regulatory region sequence-specific DNA binding
Biological process: regulation of DNA-templated transcription; regulation of gene expression
Cellular component: nucleus; nucleoplasm
Genetic constraint (gnomAD): Loss-of-function variants: 16 observed, 18.87 expected, observed/expected ratio (o/e) 0.85, 90% interval 0.57 to 1.29. The upper end of that interval is the gene's LOEUF score, 1.29, which puts it in group 5 of 6, group 1 being the genes least tolerant of losing a copy. Missense variants: 178 observed, 242.34 expected, observed/expected ratio (o/e) 0.73, 90% interval 0.65 to 0.83. Synonymous variants: 70 observed, 76.43 expected, observed/expected ratio (o/e) 0.92, 90% interval 0.75 to 1.12.
Homologues: Paralogues in human: ZNF813 (78% identical), ZNF761 (78% identical), ZNF765 (75% identical), ZNF888 (72% identical), ZNF468 (71% identical), ZNF578 (71% identical), ZNF860 (70% identical), ZNF701 (70% identical), ZNF816 (67% identical), ZNF766 (49% identical).
Diseases named in the same sentence as ZNF525 in open-access papers:
ZNF525 is named in the same sentence as 4 diseases in open-access papers, as found by Europe PMC text mining. Sharing a sentence is not in itself a finding about the gene and the disease. The quoted sentences say what the papers report.
Alzheimer disease (1 paper, 2022). A progressive, neurodegenerative disease characterized by loss of function and death of nerve cells in several areas of the brain leading to loss of cognitive function such as memory and language. "Other genes in analysis (JMY, ZNF525, and COBLL1) were not previously associated with Alzheimer’s disease." (PMID 35626321, 2022).
tumor (1 paper, 2019). "Mean expression of ZNF714 was similar in normal and tumor samples, whereas ZNF525, ZNF643, and ZNF707 fell below the detection level." (PMID 30444046, 2019).
ZNF525 also shares sentences with these, for which no sentence is quoted: cancer (2 papers); osteosarcoma (1).